MIR224 (microRNA 224)
Synonyms: hsa-mir-224; MIRN224; miRNA224
Gene: MicroRNA gene on chromosome X (151,958,578 to 151,958,658, reverse strand). Ensembl gene ENSG00000284363.
Gene Ontology:
Biological process: cellular response to amino acid stimulus; cellular response to leukemia inhibitory factor; cellular response to lipopolysaccharide; miRNA-mediated post-transcriptional gene silencing; Wnt signaling pathway
Cellular component: RISC complex
Homologues: Orthologues: chimpanzee ptr-mir-224 (100% identical), macaque mml-mir-224 (100% identical), guinea pig MIR224 (98% identical), pig ssc-mir-224 (96% identical), dog MIR224 (83% identical), rabbit MIR224 (78% identical).
Diseases named in the same sentence as MIR224 in open-access papers:
MIR224 is named in the same sentence as 1 disease in open-access papers, as found by Europe PMC text mining. Sharing a sentence is not in itself a finding about the gene and the disease. The quoted sentences say what the papers report.
ovarian carcinoma (1 paper, 2021). A malignant neoplasm originating from the surface ovarian epithelium. "However, further studies are warranted, particularly those designed to delineate the underlying molecular mechanisms involved in MIR224-associated ovarian cancers." (PMID 33920789, 2021). "Based on these results, we propose that MIR224 represents a potential biomarker for ovarian cancer." (PMID 33920789, 2021). "MIR224 performs critical gene-regulating functions involved in chemoresistance in A2780CP/A2780S and C13/OV2008 ovarian cancer cells, via regulating the PRKCD (protein kinase C delta) pathway." (PMID 33920789, 2021).